CADM2 (cell adhesion molecule 2)
Diseases named in the same sentence as CADM2 in open-access papers (continued):
Sharing a sentence is not in itself a finding about the gene and the disease.
esophageal cancer (1 paper, 2021). A primary or metastatic malignant neoplasm involving the esophagus. "For example, a study has indicated that CADM2‐ADAMTS9‐AS2 ceRNA network centered on hsa‐miR‐372, and SERPINE1‐PVT1 ceRNA network centered on hsa‐miR‐145 may be potential carcinogenic mechanisms of esophageal cancer." (PMID 34586751, 2021).
glaucoma (1 paper, 2018). Increased pressure in the eyeball due to obstruction of the outflow of aqueous humor. "We also investigated 9 novel glaucoma-associated loci from UKB in GERA, and 6 of the novel loci replicated at Bonferroni significance (near IKZF2, CADM2, near DGKG, ANKH, EXOC2, and LMX1B)." (PMID 29891935, 2018). "Here we have identified a set of genes in POAG-associated loci whose expression is altered in the RGCs (e.g., Ank, Cadm2, and Six6) and the optic nerve head (e.g., Cadm2 and Cdkn2b) in a mouse model of glaucoma." (PMID 29891935, 2018). "Based on the gene profiling in the optic nerve head tissue, Cadm2, Cdkn2b, and Tmtc2 exhibit altered expression very early and across all stages of glaucoma (early to severe)." (PMID 29891935, 2018). "These included Angpt1, Ank, Cadm2, Fmnl2, Plce1, Thsd7a, and Tmtc2 at the novel POAG/glaucoma loci identified in the current study." (PMID 29891935, 2018).
insomnia (1 paper, 2026). A sleep disorder characterized by difficulty in falling asleep and/or remaining asleep. "Fine-mapping and colocalization analyses identified shared genetic signals between cannabis use and clinical insomnia including a near-perfect colocalization at SLC39A8 and CADM2." (PMID 42064962, 2026).
mouth ulcers (1 paper, 2023). "The proteins encoded by eight genes (PMEL, ARFIP1, FAM213A, GLUL, CADM2, FAIM3, RIPK2, and DECR1) have only one SNP instrumental variable and have a association with mouth ulcers using the Wald ratio method." (PMID 37369724, 2023).
nicotine dependence (1 paper, 2021). Physical and psychological dependence on nicotine. "Regular alcohol use, problematic alcohol use, regular tobacco use, and nicotine dependence were all associated with CADM2 in the meta‐analyses." (PMID 33604983, 2021).
tumor (27 papers, 2012 to 2025). "Cadm2 is a regulatory gene encoding the CADM2 protein responsible for intercellular adhesion, and it is involved in tumor metastasis as part of the circHIAT1/miR-19a-3p/CADM2 signaling pathway." (PMID 41009560, 2025). "CADM2 suppression by miR-17 promotes tumor cell proliferation, migration, invasion, and dysregulation of the cell cycle, while HSBP2 downregulation disrupts programmed cell death, enhances clonogenic potential, and increases tumor cell survival." (PMID 41373892, 2025). "At last, we demonstrated the anti-tumor effects of circDDX17 in invasive ability were mediated by the activity of CADM2 expression via sponging miR-1279 in vitro and in vivo." (PMID 38023219, 2023). "The CADM2 was used to be reported as a tumor suppressor and is usually downregulated in several cancers." (PMID 37904118, 2023). "Our results uncovered that down-regulated SAMD12 and CADM2 exacerbated the proliferation potency, demonstrating the tumor suppression potential of SAMD12 and CADM2 in liver tumors." (PMID 37228062, 2023). "miR-25 knockdown markedly decreases tumor cell migration and invasiveness through enhancing the expression of cell adhesion molecule 2 (CADM2)." (PMID 35922753, 2022). "CADM2, a protein-coding gene, acts as a tumor suppressor in cancer through inhibiting cell migration and invasion." (PMID 36561840, 2022). "CADM2 is believed to prevent tumor progression, invasion, and metastasis by maintaining cell's polarity and adhesion." (PMID 34222474, 2021). "Chmp1A and CADM2, belonging to cell adhesion molecules family, had been found to be a tumor suppressor gene in RCC." (PMID 32038722, 2019). "Meantime, we also noticed several studies verify that promoter methylation of CADM2 is one of reasons which lead to hypo-expression of CADM2 in tumor tissues." (PMID 29506532, 2018). "In this study, we reported that CADM2 serves as a tumor suppressor that negatively control HCC metastasis." (PMID 29506532, 2018). "The transcriptional orientation of the MMTV genome relative to the transcriptional orientation of the gene in which it integrated, was determined for four genes (Usp31, Nckap5, Cadm2 and Notch4) for which there was available tumor RNA." (PMID 23131872, 2012). "Meanwhile, CADM2 expression also displayed a down-regulation in the tumor samples." (PMID 38990915, 2024). "Notably, CADM2 was verified as the direct binding target of miR-1279, and silencing the expression of CADM2 reverses the tumor suppressing effects induced by circDDX17 overexpression." (PMID 38023219, 2023). "SAMD12 and CADM2 may play an alternate role in postoperative effects and tumor size, possibly contributing to carcinogenesis." (PMID 37228062, 2023). "Moreover, silencing the expression of CADM2 reverses the tumor suppressing effects induced by circDDX17 overexpression." (PMID 38023219, 2023). "CADM2 reported as a tumor inhibiting gene could suppress the Akt signaling pathway." (PMID 38023219, 2023). "There is currently no literature on the association between CADM2 and tumor immune processes, and thus, our risk score model might suggest a new direction for future research." (PMID 34925438, 2021). "Low CADM2 expression is commonly observed in ESCC tissues, contributing to enhanced tumor growth and resistance to apoptosis." (PMID 41476448, 2025). "For instance, several down-regulated PCGs in the LL-like tumor samples, including SOCS2, CADM2, SH3TC and ENC1, are previously reported as potential tumor suppressors." (PMID 35939448, 2022). "Cell Adhesion Molecule 1 (CADM1), CADM2, CADM3 and CADM4, serve as tumor suppressors and can inhibit cancer cell proliferation and induce apoptosis." (PMID 31480483, 2019). "In order to validate the correlation between CADM2 and miR-10b expression in human HCC tissues, we firstly collected and analyzed fresh human HCC samples and corresponding non-tumor tissues from HCC resection." (PMID 29506532, 2018).
tumor (continued). "Conversely, we found the previously identified PCa driver gene LRP1B (12/17) and new candidate genes TTC28 (16/27), CADM2 (12/16), LSAMP (11/16), EYS (16/18), PTPRD (12/18), PACRG (5/6) and PDE4D (12/17) to be predominately interrupted in tumours from African patients." (PMID 36045381, 2022).
cancer (20 papers, 2015 to 2025). A tumor composed of atypical neoplastic, often pleomorphic cells that invade other tissues. "ZNF300, CSMD1, and CADM2 have been implicated in cancer cell proliferation, migration, and invasion, features mirrored by the invasive, immunologic, and angiogenic properties of placental cells." (PMID 40312437, 2025). "CADM2 dysregulation has been also implicated in the regulation of EMT process of other types of cancers." (PMID 38990915, 2024). "One of them is cell adhesion molecule 2 (CADM2), used by cancer cells in both cytoskeletal organization and cell adhesion since it plays a fundamental role in the aggregation and forming of cell clusters." (PMID 36835266, 2023). "The anti-cancer effect of quercetin could be attributed to its regulatory effect on circHIAT1/miR-19a-3p/CADM2 axis." (PMID 38990915, 2024). "Recent studies have shown that CADM2 may serve as a cancer-suppressing gene that prevents cell proliferation and metastasis." (PMID 38126999, 2023). "The overexpression of Chmp1A and CADM2 significantly suppressed cancer growth and invasion." (PMID 32038722, 2019). "Notably, miR-944 was also able to inhibit cancer cell apoptosis by targeting CADM2." (PMID 36077769, 2022). "Taken together, our study identified quercetin as a potential anti-cancer compound to reverse Palbociclib resistance and impair EMT in BC cells by targeting circHIAT1/miR-19a-3p/CADM2 axis." (PMID 38990915, 2024). "In summary, this study identified quercetin as a potential anti-cancer compound to reverse Palbociclib resistance and impair EMT in BC cells by targeting circHIAT1/miR-19a-3p/CADM2 axis." (PMID 38990915, 2024). "In contrast, miR-944 promotes the corresponding cancer cell proliferation by targeting three genes (SOCS4, CADM2, and HECW2) and participating in the LINC00899/miR-944/ESR1signaling axis." (PMID 36077769, 2022). "Additionally, the function of a few other genes, such as GBE1 and CADM2 in 3p12.1, has not been intensively studied in cancers and thus deserve further investigation." (PMID 26386145, 2015). "Many of these other potential enhancer-hijacking targets do not have well-established roles in cancer pathogenesis, however, we did notice a number of genes involved in cell adhesion (ALCAM, NCAM2, CADM2, and CDH9) and 2 SLIT and NTRK like family members (SLITRK1, SLITRK6)." (PMID 35538064, 2022).
psychiatric disorder (4 papers, 2020 to 2025). A disorder characterized by behavioral and/or psychological abnormalities, often accompanied by physical symptoms. "Furthermore, CADM2 has been reported in a GWAS study to be associated with risk-taking behavior, which is a key component that shares a significant genetic risk with several psychiatric disorders including BD22." (PMID 33168801, 2020). "Meanwhile, CADM2 was also shown to play a role in some psychiatric disorders like AUD, BD, and ADHD." (PMID 35509074, 2022). "Besides, we identified 13 risk loci for FTD, as well as seven shared loci between FTD and psychiatric disorders, and identified MAPT and CADM2 as shared risk genes by integrating cis-eQTL analysis." (PMID 35509074, 2022). "Therefore, CADM2 might act as a potential genetic link between FTD and psychiatric disorders." (PMID 35509074, 2022).
CNS tumor (1 paper, 2021). "For brain and CNS tumor samples, CADM1, CADM2, NECTIN1, and NECTIN3 were downregulated, whereas NECTIN2 was overexpressed." (PMID 34925438, 2021).
myopathy (1 paper, 2022). A disease of the muscle in which the muscle fibers do not function properly. "Forty-six candidate genes are prioritized by multiple approaches (42 for LST and 6 for MVPA; 2 overlap) and point to endocytosis (CNIH2, RAB1B, KLC2, PACS1, REPS1, DNM3, EXOC4), locomotion (CADM2, KLC2) and myopathy (MLF2, HERC1, KLC2, SIL1) as relevant pathways." (PMID 36071172, 2022).
neurodevelopmental disorder (1 paper, 2025). A behavioral and cognitive disorder with onset during the developmental period that involves impaired or aberrant development of intellectual, motor, or social functions. "Neuronal populations showed enriched expression of neurodevelopmental disorder-linked genes (NRXN3, CADM2, ZNF536) and synaptic signalling pathways." (PMID 41010342, 2025).
CADM2 also shares sentences with these, for which no sentence is quoted: anxiety disorder (2 papers); colon cancer (2); lung carcinoma (2); melanoma (2); metabolic syndrome (2); renal cell carcinoma (2); type 2 diabetes (2); allergies (1); anorexia nervosa (1); Autoimmunity (1); cardiovascular disease (1); Cognitive impairment (1); diabetes (1); fibrosis (1); gastric cancer (1); Hypertension (1); infection (1); Insulin resistance (1); irritable bowel syndrome (1); lymphoma (1); mental disorder (1); metabolic disease (1); migraine (1); myocardial infarction (1); myopia (1); non-small cell lung carcinoma (1); oral squamous cell carcinoma (1); osteosarcoma (1); ovarian carcinoma (1); pituitary adenomas (1).
A further 5 diseases each share a sentence with CADM2 in 1 paper.